PAQR6 (progestin and adipoQ receptor family member 6)
Description:
Plasma membrane progesterone (P4) receptor coupled to G proteins. Seems to act through a G(s) mediated pathway. Involved in neurosteroid inhibition of apoptosis. May be involved in regulating rapid P4 signaling in the nervous system. Also binds dehydroepiandrosterone (DHEA), pregnanolone, pregnenolone and allopregnanolone.
Synonyms: FLJ22672; PRdelta
Tractability: Antibody: UniProt places it where antibodies can reach, with high confidence; UniProt predicts a signal peptide or a membrane-spanning region; its Gene Ontology location is reachable by antibodies, with medium confidence.
Gene: Protein-coding gene on chromosome 1 (156,243,320 to 156,248,117, reverse strand). Ensembl gene ENSG00000160781.
Subcellular location: Cell membrane
Gene Ontology:
Molecular function: protein binding; signaling receptor activity
Cellular component: membrane; plasma membrane
Genetic constraint (gnomAD): Loss-of-function variants: 34 observed, 36.09 expected, observed/expected ratio (o/e) 0.94, 90% interval 0.72 to 1.25. The upper end of that interval is the gene's LOEUF score, 1.25, which puts it in group 5 of 6, group 1 being the genes least tolerant of losing a copy. Missense variants: 431 observed, 442.54 expected, observed/expected ratio (o/e) 0.97, 90% interval 0.9 to 1.05. Synonymous variants: 190 observed, 186.99 expected, observed/expected ratio (o/e) 1.02, 90% interval 0.9 to 1.15.
Homologues: Orthologues: macaque PAQR6 (98% identical), dog PAQR6 (91% identical), pig PAQR6 (91% identical), guinea pig PAQR6 (89% identical), rat Paqr6 (88% identical), mouse Paqr6 (87% identical), tropical clawed frog paqr6 (62% identical), zebrafish paqr6 (50% identical), chimpanzee PAQR6 (49% identical), Caenorhabditis elegans K11C4.2 (20% identical), Drosophila melanogaster AdipoR (18% identical), Caenorhabditis elegans paqr-1 (18% identical). Paralogues in human: PAQR5 (49% identical), PAQR9 (29% identical), PAQR8 (28% identical), PAQR7 (26% identical), PAQR4 (20% identical), ADIPOR2 (19% identical), ADIPOR1 (19% identical), PAQR3 (17% identical), MMD2 (13% identical), MMD (12% identical).
Diseases named in the same sentence as PAQR6 in open-access papers:
PAQR6 is named in the same sentence as 13 diseases in open-access papers, as found by Europe PMC text mining. Sharing a sentence is not in itself a finding about the gene and the disease. The quoted sentences say what the papers report.
bladder cancer (4 papers, 2021 to 2024). "High frequency of copy number variation of the PAQR6 gene (60%) was recently found in urinary bladder cancers, which was associated with disease progression in muscle-invasive bladder cancer patients." (PMID 34572596, 2021). "This is consistent with previous observations of PAQR6 acting as a tumor-promoting factor in prostate and bladder cancer." (PMID 39742277, 2024). "In this retrospective study, we have focused on the prognostic value of CEP63, FOSL2 and PAQR6 in bladder cancer." (PMID 34041036, 2021). "Then, 9 target genes that were differentially expressed between bladder cancer and normal samples were screened (FDR < 0.05), in which upregulated expression of RHBG, PAQR6, CLK2, KRTCAP2, FLAD1, HCN3 were correlated with bad survival of patients with bladder cancer." (PMID 36186809, 2022).
breast carcinoma (1 paper, 2022). "Interestingly, when we repeated our analysis utilizing a different breast cancer database (TCGA), we confirmed that decreased expression of PAQR6 had the worst overall survival (OS) for Luminal-A breast cancer patients, validating our previous results using a separate cohort." (PMID 35971177, 2022).
endometrial cancer (1 paper, 2021). Primary or metastatic malignant neoplasm involving the endometrium (mucous membrane that lines the endometrial cavity). "Specifically, PAQR6 gene upregulation or copy number gain was associated with an unfavorable prognosis in the prostate, bladder, and endometrial cancers." (PMID 35127538, 2021). "In human endometrial cancers, increased PAQR5 expression was associated with a favorable patient prognosis, whereas increased PAQR6 expression was associated with a poor prognosis in prostate cancers." (PMID 35127538, 2021).
endometriosis (1 paper, 2020). The growth of functional endometrial tissue in anatomic sites outside the uterine body. "Using RT-qPCR, we observed that the expression of PAQR7, PAQR8, PAQR5, and PAQR6 genes was significantly downregulated in the eutopic endometrium of patients with endometriosis compared with the endometrium of women without the disease." (PMID 32733932, 2020). "The analysis of gene expression showed that PAQR7 and PAQR5 expression was lower in both eutopic and ectopic endometrium as compared to the endometrium of women without endometriosis, whereas the expression of PAQR8 and PAQR6 was only reduced in eutopic endometrium." (PMID 32733932, 2020).
measles (1 paper, 2023). A highly contagious viral infection caused by the measles virus. "In measles, including six in whole blood (SOAT1, COLGALT2, AC021860.1, HCG11, METTL21B, and MRPL10), six in the lung tissue (GSTM4, PAQR6, RP11-617D20.1, SNX8, METTL21B, and ANKRD27), and two in the transformed fibroblast cells (CBWD2, and TSFM)." (PMID 37020999, 2023).
nasopharyngeal carcinoma (1 paper, 2023). A carcinoma arising from the nasopharyngeal epithelium. "For example, SOAT1 has been linked to the development of stomach cancer, and pancreatic cancer; HCG11 may influence the development of nasopharyngeal carcinoma; the PAQR6 gene has also been associated with several cancers." (PMID 37020999, 2023).
prostate carcinoma (1 paper, 2021). A carcinoma that arises from epithelial cells of the prostate gland. "Altogether, these results demonstrated a tight association of PAQR6 upregulation with higher Gleason score, advanced tumor stage, higher fPAS/tPSA ratio, and quick disease relapse in primary prostate cancers." (PMID 34572596, 2021). "Our comprehensive analysis discovered that PAQR6 expression was significantly upregulated in primary prostate cancers, which was strongly correlated with disease progression and patient survival outcomes." (PMID 34572596, 2021). "In prostate cancer tissues, PAQR6 expression was significantly upregulated, while all other genes were largely downregulated compared to normal prostate tissues." (PMID 34572596, 2021). "PAQR6 upregulation in primary cancer tissues is a novel prognostic biomarker for disease progression, overall, and progression-free survival in prostate cancers." (PMID 34572596, 2021). "Our results showed that PAQR6 gene expression was significantly upregulated in prostate cancers and correlated with quick disease progression and worse survival outcomes." (PMID 34572596, 2021). "In this study, we found that PAQR6 expression was enhanced by DHT stimulation in prostate cancer LNCaP cells, which was blocked by AR antagonist Bicalutamide." (PMID 34572596, 2021). "In another RNA-seq dataset generated from 116 early-onset prostate cancers (diagnosis ≤ 55 years), a significant increase of PAQR6 gene expression was found in late-stage (pT3b-pT4) patients compared to early-stage (pT2a/b) patients." (PMID 34572596, 2021). "Furthermore, PAQR6 expression was strongly correlated with the clinical biomarker fPSA/tPSA ratio in a cohort of 37 treatment-naive prostate cancers." (PMID 34572596, 2021). "Our results showed that PAQR6 expression was significantly upregulated in primary prostate cancers." (PMID 34572596, 2021). "Similarly, PAQR6 upregulation was reported in prostate cancer tissues and correlated with poor survival outcomes." (PMID 34572596, 2021). "Conversely, in neuroendocrinal prostate cancer (NEPC) tissues, PAQR6 expression was significantly lower, but PAQR7/8 expression was higher than castration-resistant prostate cancer (CRPC) tissues." (PMID 34572596, 2021). "PAQR6 was upregulated about 2-fold, and PAQR7/8 was downregulated more than 1.5-fold in prostate cancers compared to normal prostatic tissues." (PMID 34572596, 2021).
tumor (6 papers, 2021 to 2025). "PAQR6 upregulation was associated with cancer grade (Gleason score), tumor stages (TNM categories), disease progression (quick relapse), and survival outcomes." (PMID 34572596, 2021). "PAQR6 is significantly upregulated in PRAD tissues and is closely associated with a higher pathological stage of the tumor, ratio of free-prostate-specific antigen/total-PSA, Gleason score, and shorter OS." (PMID 40548257, 2025). "Similarly, PFS, assessed using the GSE29609 dataset, evaluates the time to disease progression, including tumor recurrence or metastasis, offering critical insights into whether elevated PAQR6 expression is linked to more aggressive disease behavior or shorter recurrence-free intervals." (PMID 39742277, 2024). "Our study identifies a strong association between PAQR6 and angiogenesis-related pathways, particularly through its correlation with EZH2, a well-known oncogene involved in cell cycle regulation and tumor progression." (PMID 39742277, 2024). "Results showed that compared with the control group, copy numbers of 3 genes, CEP63 (p<0.01), FOSL2 (p<0.01) and PAQR6 (p<0.01) were significantly gained in tumor tissues." (PMID 34041036, 2021). "These circRNAs may competitively bind to miRNAs, thereby increasing PAQR6 expression and promoting tumor progression." (PMID 39742277, 2024). "We discovered significant differences in the expression of PAQR6 across various tumor lymph node status clinical samples, suggesting this key mPR may be potentially involved in lymph node infiltration mechanisms." (PMID 35971177, 2022). "Copy numbers of CEP63, FOSL2 and PAQR6 were gained in 219 tumor samples." (PMID 34041036, 2021). "Although both PAQR6 upregulation and PAQR5 downregulation were significantly correlated with tumor pathological stages, only PAQR6 upregulation was associated with Gleason score, free-prostate-specific antigen (fPSA)/total-PSA (tPSA) ratio, and patient overall survival outcomes." (PMID 34572596, 2021). "The link between PAQR6 and hypoxia-induced factors such as HIF1A suggests that it may act downstream of hypoxia-regulated pathways, integrating immune suppression and angiogenesis in the tumor microenvironment." (PMID 39742277, 2024).
cancer (5 papers, 2021 to 2024). A tumor composed of atypical neoplastic, often pleomorphic cells that invade other tissues. "DSS, which measures survival probability without death specifically attributable to KIRC, was analyzed using the TCGA-KIRC dataset, providing insights into the relationship between PAQR6 expression and cancer-specific mortality." (PMID 39742277, 2024). "This network not only sheds light on the post-transcriptional regulation of PAQR6 but also aligns with previous research emphasizing the prognostic and functional significance of ceRNA networks in cancer." (PMID 39742277, 2024). "Next, we performed expression profiling based on family cancer history and observed significant differential expression patterns for PAQR6, PGRMC1/2, and nPRs among HCC patients." (PMID 36980321, 2023). "In conclusion, we found that the cancer-related CNVs of CEP63, FOSL2 and PAQR6 were competent in evaluating recurrence or progression risk for BC patients and may be used for the risk group stratifications in the future." (PMID 34041036, 2021). "Moreover, the number of invading cells was significantly reduced compared to the control group, demonstrating that the knockdown of PAQR6 could inhibit cancer cell invasion." (PMID 39742277, 2024).
PAQR6 also shares sentences with these, for which no sentence is quoted: hepatic cancers (1 paper); pancreatic cancer (1); stomach cancer (1); type 2 diabetes (1).